AR (androgen receptor)
Diseases named in the same sentence as AR in open-access papers (continued):
Sharing a sentence is not in itself a finding about the gene and the disease.
tumor (continued). "By binding the cytoskeletal protein filamin A and activating protease cascades via β1-integrin-dependent signaling, this AR variant triggers ECM remodeling and creates permissive tracks for tumor-cell dissemination." (PMID 41514658, 2025). "In this same study, it was also noted that enzalutamide therapy showed significant tumor suppression in cell lines of AR-positive RCC." (PMID 41034844, 2025). "The tumor suppression function is partially through AR targets, such as PTEN and DNA damage response genes." (PMID 41228208, 2025). "Novel strategies based on the genetic signature of the tumour lead to promising therapies with androgen receptor (AR)‐targeted drugs, antibody‐drug conjugates (ADC), poly ADP‐ribose polymerase inhibitors (PARPI), or tyrosine kinase inhibitors (TKI)." (PMID 40434213, 2025). "In parallel, pTVG-AR was developed to target the ligand-binding domain of the androgen receptor (AR), a critical driver of tumor progression, especially in the castration-resistant setting." (PMID 40943636, 2025). "Mainly, the analyzed studies suggest that radiomic features can be used to predict the pCR response to NAC, surpassing conventional metabolic markers, the evaluation of androgen receptor status, and tumor subtype classification." (PMID 40941718, 2025). "Compared to other ARPIs, Enzalutamide exhibits a higher binding affinity to the AR, a critical driver of castration resistance and tumor progression in prostate cancer." (PMID 40430550, 2025). "Mice with AR-positive PCa exhibited suppressed cell proliferation, decreased tumor growth, and lowered blood PSA levels in preclinical investigations using fatostatin." (PMID 41009695, 2025). "Immunohistochemical analyses further corroborated this finding: Of 347 AR+/NE– PC samples, AR– tumor cells were present in more than 33%." (PMID 40493417, 2025). "In summary, STARD4 functions as a tumour suppressor in PCa by regulating cholesterol metabolism and modulating AR signalling." (PMID 41331871, 2025). "AR-imprinted TREM2/SPP1 TAMs cluster near tumor nests, CAFs, and vasculature; specifically enriched in the bone metastatic niche." (PMID 41488638, 2025). "AR primarily promotes carcinogenesis in bladder and prostate tissues by modulating inflammation and fostering a pro‐tumor immune microenvironment." (PMID 40007149, 2025). "When tumor progression occurs despite the initial androgen deprivation therapy, alternative pathways of androgen receptor activation are applied." (PMID 40115018, 2025). "In this regard, it was reported that epigallocatechin gallate (EGCG) can inhibit expression levels of androgen receptor (AR) and nuclear translocation in a tumor xenograft model." (PMID 40336533, 2025). "In light of the significant role of AR signaling in the progression of PCa and resistance to Enz, we integrated tumor cell sub-clusters 0, 1, 2, and 3, which exhibited AR response, and identified them as key module traits." (PMID 40849495, 2025). "Among these AR antagonists, PPARγ agonists have demonstrated the potential to inhibit tumor growth by disrupting pathways involved in cellular proliferation, highlighting their therapeutic value in targeting BCa." (PMID 40806474, 2025). "The sustained STAT3 activity not only promotes NED but also upregulates anti-apoptotic and pro-survival genes, enabling tumor cells to evade AR-targeted therapies." (PMID 40303302, 2025). "We chose to set the AR-positivity cutoff to 10% tumor cells because this was the most frequently observed prevalence of AR-positivity in the reported studies." (PMID 40150035, 2025). "In a smaller subset of tumours, AR activity is lost and enhanced cellular plasticity confers phenotypes – such as neuroendocrine and stem-like states – that promote metastasis, therapy resistance, immune evasion and other oncogenic features." (PMID 40163908, 2025). "In these tumors, AR activation appears to exert anti-proliferative effects, potentially inhibiting tumor growth and metastasis." (PMID 40286049, 2025).
tumor (continued). "Antiandrogen therapy or AR knockdown suppresses this pathway to promote NK cell-mediated tumor clearance." (PMID 40852728, 2025). "Using UMAPs, we identified 3 tumor cell clusters that differed in their expression of AR signaling and NE transcription factors." (PMID 40493417, 2025). "In CRPC, tumor cells can continue to grow even when AR signaling is blocked with the help of AR-independent pathways." (PMID 41235005, 2025). "The NF-κB signaling pathway is an important regulatory factor of inflammation in the tumor microenvironment and can interact with AR signaling through various mechanisms." (PMID 40008000, 2025). "The molecular subtypes identified through AR-DEGs provide valuable insights into the complex interplay between immune rejection mechanisms and tumor progression in LIHC." (PMID 41451236, 2025). "In contrast, CRPC displays selective upregulation of specific M‐phase cell cycle genes by AR, enabling tumour growth even under androgen‐deprived conditions." (PMID 39763034, 2025). "We also detected the expressions of PSA, androgen receptor (AR), estrogen receptor (ER), and progesterone receptor (PR) in the tumor." (PMID 39974302, 2025). "AR expression in ≥10% of tumor cells assessed by means of DIA was found to be an independent predictor of worse prognosis in TNBC." (PMID 39851328, 2025). "The protective role of AR in ER-positive breast cancer makes it a potential target for regulating tumor growth." (PMID 40023399, 2025). "This indicates that PrSt/MSF-derived PSAP/Sap C stimulates PSAP transcription within tumor cells through paracrine signaling, possibly by enhancing AR activity, which forms a feed forward loop involving PSAP/Sap C and AR signaling in PCa cells." (PMID 40801564, 2025). "In primary or metastatic prostate tumors undergoing ADT, stromal cells can stimulate AIS activation of AR through paracrine Hh signaling within the tumor microenvironment." (PMID 39785769, 2025). "Tumours resistant to tamoxifen show higher levels of AR expression than tamoxifen-sensitive tumours." (PMID 41301715, 2025). "PCa is a hormone-dependent tumor that relies on AR signaling to sustain tumor growth in its early stages." (PMID 40821114, 2025). "For example, the combination of an antiandrogen drug Bicalutamide and radiotherapy significantly attenuated tumor growth in the AR-positive compared to the AR-negative animal model." (PMID 40150035, 2025). "This locally synthesized androgen is sufficient to activate the AR signaling pathway, further promoting tumor growth." (PMID 41235005, 2025). "LNCaP and LAPC4 cells represent an earlier state of hormone sensitivity in an untreated tumor, and 22Rv1 cells are AR-positive cells with treatment-acquired resistance to hormone therapy and antiandrogen." (PMID 40906535, 2025). "Overexpression of AR allows tumor cells to survive and grow despite low androgen levels during therapy." (PMID 39757310, 2025). "Inhibiting the androgen-AR axis reprograms the tumor microenvironment, enhancing effector T cell differentiation and improving the response to anti-PD-1 immunotherapy, highlighting the potential for targeting androgen signaling in cancer treatment." (PMID 40438106, 2025). "To gain more insight into the tumor-relevant pathways affected by MED12 knockdown or miRNA modulation, we determined the protein expression of MED12, the androgen receptor (AR), the androgen receptor splice variant V7 (AR-V7) and c-Myc." (PMID 40133664, 2025). "In contrast, FOXO3a, which commonly functions as a tumor suppressor, can inhibit the transcriptional activity of ER and AR." (PMID 40003882, 2025). "Taken together, MCL1 inhibition demonstrated anti-tumor activity in several PCa models, including those resistant to treatments that target the AR, which remains a major unmet clinical need in PCa medicine." (PMID 41438049, 2025).
tumor (continued). "Several studies suggest that AR expression is positively correlated with tumor pathological grade, with grade 4 tumors demonstrating the most elevated expression levels." (PMID 41153666, 2025). "In line with these advancements, several studies have demonstrated that the AR can be activated independently of androgens, allowing tumor progression to continue despite hormonal deprivation." (PMID 40868127, 2025). "We critically examine how peroxisomal dysfunction influences tumor biology with particular emphasis on its interaction with AR signaling." (PMID 40647540, 2025). "Matrigel-free cultures retain AR-active tumor heterogeneity and intermediate cells, whereas Matrigel drives basal-like overgrowth." (PMID 41562091, 2025). "While certain tumor regions exhibit high AR activity, other areas demonstrate reduced AR signaling or enrichment in AR-independent pathways." (PMID 40940870, 2025). "A recent study from our group identified chimeric AR half-sites as a distinctive feature of tumor-specific AR enhancer circuitries, which are activated by the abnormal gain of NSD2 methyltransferase activity." (PMID 40570057, 2025). "Early-phase studies suggest that AR blockade can induce tumor shrinkage and disease stabilization, offering an alternative strategy for patients lacking other targeted options." (PMID 41373752, 2025). "We also observed a negative regulatory relationship between this loop and AR/PSA in subcutaneous tumor tissues." (PMID 40470696, 2025). "In BCa cell lines such as T24 and 5637, miR-124 functions as a tumor suppressor by directly targeting AR mRNA, thereby inhibiting androgen-induced proliferation and migration." (PMID 40806474, 2025). "While CAFs exhibit low baseline AR signaling activity that promotes tumor progression independently of ADT, paradoxically, AR pathway inhibition in CAFs triggers compensatory cytokine secretion to sustain tumor growth." (PMID 40607407, 2025). "Aside from this, it was revealed in the report that several genes are known to promote tumor growth and survival independently of AR signaling." (PMID 40429793, 2025). "PCa remains a significant cause of cancer-related mortality worldwide, with androgen receptor (AR) signaling playing a central role in tumor initiation and progression." (PMID 40427696, 2025). "AR expression was positively correlated with tumor-originated vasculogenesis in ccRCC patients, suggesting a tumor-promoting role, which was validated in in vitro experiments, possibly through modulating the lncRNA-TANAR/TWIST1 signaling pathway." (PMID 41228208, 2025). "For example, higher AR expression has been correlated with lower tumor grade and better overall survival in dogs, particularly in those with estrogen receptor-positive tumors." (PMID 40286049, 2025). "A recent study demonstrated that microbiota-derived bile acids drive anti-tumor immunity by antagonizing the host androgen receptor (AR)." (PMID 41050671, 2025). "Recent evidence challenges the conventional view of AR solely as a driver of proliferation, revealing its paradoxical capacity to induce cellular senescence and act as a tumor suppressor under specific conditions currently exploited in clinical trials." (PMID 41264145, 2025). "For example, when Arg-3 of the histone H4 (H4R3) is methylated by PRMT1, the acetyltransferase p300 is recruited to make further modifications that can activate the tumor specific androgen receptor (AR) target genes." (PMID 41301411, 2025). "Enzalutamide is a highly potent androgen receptor pathway inhibitor (ARPI) that exerts its effects on tumor cells through multiple mechanisms." (PMID 40430550, 2025). "This connection between AR signaling, immune interactions, and patient prognosis underscores its potential as a key driver of sex-specific tumor aggressiveness and therapeutic response in males." (PMID 40458476, 2025).
tumor (continued). "Short-term hormonal treatment appeared to reduce tumor cell AR staining and increase tumor cell apoptosis in bone metastases, while leaving cell proliferation (Ki67) and PSA expression unaffected." (PMID 40841830, 2025). "Targeting ACSM3 resulted in reduced tumor growth, revealing a link between AR and lipid metabolism, and future development of drugs targeting ACSM1 and ACSM3 is expected to explore new therapies in combination with traditional ADT therapy." (PMID 41281744, 2025). "While direct evidence of ACLY’s role in PCa is limited, its involvement in feedback loops with ACLY/AMPK/AR in other cancers suggests potential implications for tumor growth and therapy resistance in PCa." (PMID 41009695, 2025). "We and other groups have identified tumor alterations that reactivate AR signaling during treatment with an ARSI2,22–29." (PMID 41193657, 2025). "The interaction between androgen receptor signaling and the tumor microenvironment is intricate, exhibiting both tumor-promoting and tumor-suppressing effects." (PMID 40356745, 2025). "Though NKX3.1 is traditionally thought of as a tumor suppressor, it has been previously reported to promote cancer cell survival by cooperating with AR." (PMID 39858088, 2025). "Androgens promote T cell exhaustion in tumor-infiltrating CD8+ T cells by suppressing effector molecule production via AR signaling, exacerbating male-biased progression in malignancies such as bladder, colorectal, hepatocellular, and cutaneous cancers." (PMID 41019050, 2025). "These exosomes were loaded with inhibitors for EZH2 and the AR, and studies in both cell cultures and animal models demonstrated significant tumor suppression, highlighting their potential as a therapeutic tool for CRPC." (PMID 41235005, 2025). "In tumours that coexpress full-length AR, this involves dampened transcriptional responses and disruption of the autoregulatory loop that modulates AR levels." (PMID 40221372, 2025). "In melanoma, downregulation of AR signaling has been shown to increase macrophage infiltration, inhibit tumor progression, and offer potential avenues for immunotherapy." (PMID 40303343, 2025). "Further studies is needed to elucidate AR’s role in tumor immunity and propose combining AR modulation with ICIs as a potential therapeutic strategy." (PMID 40361336, 2025). "Biologically, ERG rearrangements facilitate oncogenesis by promoting androgen receptor (AR)-regulated transcriptional pathways, which enhance tumour invasion and progression." (PMID 40165885, 2025). "DOX resistance, however, was enhanced on AR activation in both models, as reflected by the increased tumor volume compared between DOX and DHT + DOX groups." (PMID 40940753, 2025). "Circulating tumor DNA (ctDNA) acts as an early biomarker of the efficacy of androgen receptor signaling inhibitor (ARSI) therapy." (PMID 40377440, 2025). "Clinical studies have also indicated that the detection of continuous AR nuclear translocation in circulating tumor cells predicts poor outcomes with docetaxel." (PMID 41079787, 2025). "Specific integrins, such as αvβ6 and α6β1, promote CRPC growth by activating pathways that enhance AR activity even in low-androgen conditions, contributing to therapy resistance and tumor aggressiveness." (PMID 41235005, 2025). "This subtype exhibits reduced dependence on androgen receptor (AR) signalling compared to ERG-positive tumours, contributing to resistance to AR-targeted therapies such as androgen deprivation therapy (ADT)." (PMID 40165885, 2025). "While metastatic tumor samples and cell line models have been critical to understanding how AR reactivation occurs, they often lack the ability to fully replicate the complexity and heterogeneity of the clinical TME, which includes immune and stromal factors." (PMID 40427518, 2025).
tumor (continued). "In PCa, TMPRSS2 is directly regulated by AR transcription and regulated by androgen in vivo, which promotes tumor cell invasion and metastasis to distant organs and increases disease severity and infection risk." (PMID 40145441, 2025). "Second, our study revealed differential molecular and immune characteristics associated with FOLH1 expression within specific tumor sites, and an association of FOLH1 with AR signaling." (PMID 41056440, 2025). "Therapeutically, these molecular tumours continue to depend on androgen receptor (AR) signalling making them responsive to androgen deprivation therapy (ADT) and AR-targeted agents such as enzalutamide and abiraterone." (PMID 40165885, 2025). "The lncRNA XIST, which is overexpressed in BCa tissues and cell models, acts as a competing endogenous RNA (ceRNA), sequestering miR-124 and restoring AR expression, thereby increasing tumor aggressiveness." (PMID 40806474, 2025). "This amplification renders the tumor hypersensitive to the low androgen concentrations present after medical or surgical castration, enabling continued AR signaling and disease progression." (PMID 41235005, 2025). "The CWR-R1ca cells represent an ideal in vivo model to study tumor distant recurrences and metastatic patterns, as this cell line is highly metastatic and expresses wild-type AR, AR-v7, and PSA." (PMID 40362754, 2025). "Subsequent rescue experiments demonstrated that KIF15 overexpression reduced the anti-tumor efficacy of ATR-I against AR+ and AR− CRPC cells, indicating that ATR-I suppressed the CRPC progression through targeting KIF15." (PMID 40087774, 2025). "Encouragingly, early trial results have demonstrated significant reductions in AR protein levels and anti-tumor activity in patients." (PMID 39851497, 2025). "In turn, myCAFs typically exhibit low AR expression, increased motility, and enhanced matrix contractility, and can promote tumor proliferation via secretion of pro-inflammatory mediators." (PMID 41514658, 2025). "Innovative approaches, including RNA interference (RNAi) strategies that silence AR expression, have shown potent anti-tumor effects in vitro and in vivo." (PMID 40940929, 2025). "Its development is closely related to androgen receptor (AR) activation and aberrant nuclear factor kappa B (NF-κB) signaling, which favors tumor progression, aggressiveness, and resistance to treatments." (PMID 41149747, 2025). "Elevated androgen levels in men suppress CD8+ T cell function through androgen receptor (AR) signaling, promoting T cell exhaustion and reducing anti-tumor immunity." (PMID 40028339, 2025). "Still, PSMA expression heterogeneity—regulated by androgen receptor (AR) signaling and influenced by tumor dedifferentiation—remains a critical determinant of efficacy." (PMID 41374949, 2025). "Although PCa luminal epithelial cells were universally AR-positive, regions that were PSA (and/or AR) activity–high were mutually exclusive to tumor foci that were expressing high levels of HER2, and vice versa." (PMID 40906535, 2025). "From a therapeutic perspective, combined inhibition of AR (androgen receptor) signaling and GLS activity yields synergistic anti-tumor effects in AR-sensitive cells." (PMID 41179661, 2025). "From a mechanistic perspective, tumor cells adapt by acquiring a more aggressive phenotype and reducing their dependence on AR signaling, while instead activating alternative survival pathways." (PMID 41373813, 2025). "The elevated AR expression enables tumor cells to remain sensitive to low concentrations of androgens, maintaining the activity of the AR signaling pathway even in conditions of extremely low exogenous androgen supply." (PMID 40008000, 2025). "Expression of another AR-driven gene, Tmprss2, was also decreased in these tumor areas with low ERG." (PMID 41321318, 2025). "NRG1 promotes androgen resistance and CRPC progression through multiple mechanisms, including bypassing AR signaling and modulating the tumor microenvironment." (PMID 40740239, 2025).